DRAM1 (DNA damage regulated autophagy modulator 1)
Description:
Not involved in p73/TP73-mediated autophagy.
Synonyms: DRAM; FLJ11259
Tractability: Antibody: UniProt predicts a signal peptide or a membrane-spanning region.
Gene: Protein-coding gene on chromosome 12 (101,877,314 to 102,012,130, forward strand). Ensembl gene ENSG00000136048.
Subcellular location: Lysosome membrane
Gene Ontology:
Molecular function: protein binding
Biological process: regulation of autophagy; cellular response to oxygen-glucose deprivation
Cellular component: cytoplasm; lysosome; lysosomal membrane
Genetic constraint (gnomAD): Loss-of-function variants: 10 observed, 14.95 expected, observed/expected ratio (o/e) 0.67, 90% interval 0.41 to 1.13. The upper end of that interval is the gene's LOEUF score, 1.13, which puts it in group 4 of 6, group 1 being the genes least tolerant of losing a copy. Missense variants: 177 observed, 185.82 expected, observed/expected ratio (o/e) 0.95, 90% interval 0.84 to 1.08. Synonymous variants: 83 observed, 73.8 expected, observed/expected ratio (o/e) 1.12, 90% interval 0.94 to 1.35.
Homologues: Orthologues: chimpanzee DRAM1 (100% identical), pig DRAM1 (95% identical), dog DRAM1 (95% identical), macaque DRAM1 (95% identical), mouse Dram1 (95% identical), rat Dram1 (95% identical), tropical clawed frog dram1 (63% identical), zebrafish dram1 (47% identical), Drosophila melanogaster CG4025 (35% identical), Caenorhabditis elegans C33A11.2 (25% identical), Caenorhabditis elegans W03A5.2 (20% identical). Paralogues in human: DRAM2 (41% identical), TMEM150B (27% identical), TMEM150A (24% identical), TMEM150C (21% identical).
Diseases named in the same sentence as DRAM1 in open-access papers:
DRAM1 is named in the same sentence as 76 diseases in open-access papers, as found by Europe PMC text mining. Sharing a sentence is not in itself a finding about the gene and the disease. The quoted sentences say what the papers report.
glioblastoma (13 papers, 2013 to 2025). The most malignant astrocytic tumor (WHO grade IV). "In glioblastoma CSCs, the autophagy-associated factors DRAM1 and p62 were highly expressed, and subsequent activation of mitogen-activated protein kinase and c-MET had a role in cell migration and invasion." (PMID 30166520, 2018). "DRAM1 was highly expressed in glioblastoma multiforme (GBM) and was associated with shorter overall survival in GBM patients, and knockdown of DRAM1 inhibited the invasion and migration capacity of glioblastoma stem cells." (PMID 32393790, 2020). "Knock down of P62 and DRAM1 in mesenchymal glioblastoma tumors results in a decrease in aggressiveness and invasion of the glioblastoma stem cells." (PMID 33573362, 2021). "Highly-expressed DRAM1 is positively associated with shorter overall survival in GBM (glioblastoma multiforme) patients, and knockdown of DRAM1 inhibits p62-mediated autophagy, leading to decreased motility and invasion in GBM stem cells." (PMID 32943616, 2020). "In addition to the proliferation of cancer cells, autophagy activation has been shown to cause invasion of hepatocellular carcinoma cells by enhancing MMP-9 expression and glioblastoma cells by regulating DRAM1 and p62." (PMID 25704884, 2015). "Consistent with our previous findings, the expressions of NUP107, DRAM1, RNF19A, PXDN, HEY2, F2R, and BMP2 were up-regulated in gliomas (glioblastoma multiforme + lower grade glioma)." (PMID 36245971, 2022). "In glioblastoma, the autophagy regulator p62/SQSTM1 and DNA damage-regulated autophagy modulator 1 (DRAM1) is highly expressed in CSCs and control their migrative and invasive capacities." (PMID 33194736, 2020). "It was also reported that DRAM1 and SQSTM1 regulated cell migration and invasion of glioblastoma stem cells." (PMID 23696801, 2013). "However, another study showed high expression of both DRAM1 and SQSTM1/p62 in glioblastoma, where they regulate cell migration and invasion and are associated with shorter or poor overall survival." (PMID 38203743, 2024). "Further, we collected experimentally validated genes that could contribute to the invasive ability of glioblastoma cells (such as ZEB1, HNRNPC, WNT5A, and DRAM1) to evaluate the invasive scores for each cell (see section “Materials and Methods”)." (PMID 33505440, 2020).
breast carcinoma (11 papers, 2015 to 2026). "Upregulation of DRAM1 has been associated with increased levels of irradiation-induced autophagy in breast cancer cells." (PMID 32393790, 2020). "DRAM1 is also targeted by miR-26b in breast cancer cells and both overexpression of miR-26b and inhibition of DRAM1 reduced IR-induced autophagy." (PMID 32585857, 2020). "We present evidence that NMI sensitizes breast cancer cells to cisplatin treatment through DRAM1 dependent autophagy." (PMID 26146406, 2015). "This indicates the importance of NMI and DRAM1 in determining sensitivity of breast cancer to cisplatin." (PMID 26146406, 2015). "Our TCGA database analysis reveals concurrent expression of NMI and DRAM1 in breast cancer specimens." (PMID 26146406, 2015). "They showed that miR-199a-5p was closely involved in basal and irradiation-induced autophagy through direct action of 3′UTR of DRAM1 gene and could affect radiation sensitivity of breast cancer." (PMID 31636666, 2019). "Based on this observation we tested if NMI modulation of DRAM1 may indeed affect breast cancer cells sensitivity to drug treatment." (PMID 26146406, 2015). "Based on our functional and mechanistic findings NMI and DRAM1 play key roles in determining the response of breast cancer to cisplatin and we suggest that NMI and DRAM1 levels may offer additional parameters towards these patient considerations." (PMID 26146406, 2015).
tuberculosis (7 papers, 2017 to 2023). A chronic, recurrent infection caused by the bacterium Mycobacterium tuberculosis. "Our previous work in a zebrafish tuberculosis model showed that host defense against Mycobacterium marinum (Mm) is impaired by deficiencies in xenophagy receptors, optineurin (Optn) or sequestome 1 (p62), and Damage-regulated autophagy modulator 1 (Dram1)." (PMID 38264729, 2023). "Transcriptome analysis of zebrafish larvae with mycobacterial granulomas revealed upregulation of the gene encoding DNA-damage regulated autophagy modulator 1 (Dram1), whose human counterpart (DRAM1) is associated with an interferon-inducible expression signature in tuberculosis patients." (PMID 33138004, 2020). "Previously, we have proposed DRAM1 as a host resistance factor for tuberculosis (TB) and a potential target for host-directed anti-infective therapies." (PMID 32332700, 2020). "DRAM1 is one of the upregulated DE-mRNAs in the Control vs. WT group and may be benefit to macrophage resistance to M. tb." (PMID 36992931, 2023). "Since M. marinum infection in zebrafish mimics aspects of human tuberculosis, further research into the Dram1-mediated selective autophagy pathway could help to develop novel strategies for host-directed anti-tuberculosis therapy." (PMID 28698482, 2017). "It was recently reported that acidification of mycobacterium marinum (Mm)-containing vesicles was strongly reduced in DRAM1 mutants in tuberculosis (TB) model." (PMID 32943616, 2020). "In this study we utilized different zebrafish mutant lines and the well-established zebrafish tuberculosis model to study the interaction of autophagy receptors of the SLR family, Optn and p62, and the autophagy modulator Dram1 in the host defense against mycobacterial infection." (PMID 38264729, 2023).
hepatocellular carcinoma (6 papers, 2015 to 2020). A malignant tumor that arises from hepatocytes. "It has been reported that DRAM1-mediated autophagic apoptosis is inhibited by activation of the PI3K/AKT signaling pathway in hepatoma, which also plays a crucial role in drug-resistant AML." (PMID 31636666, 2019).
glioma (5 papers, 2021 to 2024). A benign or malignant brain and spinal cord tumor that arises from glial cells (astrocytes, oligodendrocytes, ependymal cells). "In our study, the results of human tissue-based IHC staining and QRT-PCR experiments well confirmed the biological value of F2R, HEY2, PXDN, RNF19A, SCG5, and DRAM1 in glioma." (PMID 36245971, 2022). "BMP2 and HEY2 were identified as protective factors (HR < 1), and NUP107, DRAM1, F2R, PXDN, RNF19A, and SCG5 were identified as risk factors for glioma (HR > 1)." (PMID 36245971, 2022). "Notably, the key regulator of selective autophagy p62/SQSTM1 and DNA damage-regulated autophagy modulator 1 (DRAM1) are both highly expressed in glioma CSCs (GSCs)." (PMID 37886168, 2023). "Thus, utilizing the expression levels of LC3B, SQSTM1/p62, and DRAM1 to assess autophagy status in glioma patients could be potential predictive markers." (PMID 38203743, 2024). "QRT-PCR further supported significantly higher DRAM1 and lower SCG5 relative mRNA expression in gliomas." (PMID 36245971, 2022). "It is worth mentioning that we observed an inverse correlation between DRAM1 expression and carmustine (a chemotherapeutic drug recommended by the latest National Comprehensive Cancer Network (NCCN) guidelines for the treatment of glioma)." (PMID 36245971, 2022).
lung carcinoma (5 papers, 2020 to 2024). "The present study identified EGFR-AS1/miR-524-5p/DRAM1 as a novel signaling pathway associated with lung cancer progression and comprehended the mechanism of miR-524-5p and DRAM1 in lung cancer pathogenesis." (PMID 35222643, 2022). "Taken together, these results suggest that DRAM1 is negatively associated with poor outcomes in lung cancer progression." (PMID 32943616, 2020). "Additionally, the Kaplan–Meier survival plot clearly revealed that low DRAM1 mRNA level was associated with a poor prognosis for the overall survival time of lung cancer patients." (PMID 32943616, 2020). "For the first time, we reported DRAM1 as a potential target of miRNA-524-5p and elucidated its role in lung cancer." (PMID 35222643, 2022). "Considering the vital role of miR-524-5p in lung cancer prognosis, we explored its potential in regulating DRAM1 expression." (PMID 35222643, 2022). "Sections of lung cancer tissues were stained with specific DRAM1 and EGFR antibodies to verify the correlation between DRAM1 and EGFR, and specimens with high DRAM1 staining were negatively correlated with EGFR staining." (PMID 32943616, 2020). "In addition, the inhibition of miR-524-5p diminished DRAM1 protein expression and promoted lung cancer cell invasion." (PMID 35222643, 2022). "Interestingly, a few months later, another study showed that DRAM1 suppresses the development of lung cancer by promoting autophagy-related EGFR degradation." (PMID 35529878, 2022). "ITGB1 and DRAM1 were also abnormally expressed in many types of cancer including lung cancer." (PMID 35529878, 2022). "We further investigated the role of DRAM1 in lung cancer cell biological processes." (PMID 35222643, 2022). "In summary, these in vitro and in vivo studies uncover a novel mechanism through which DRAM1 suppresses oncogenic properties of NSCLC by regulating EGFR trafficking and degradation and highlights the potential value of DRAM1 as a prognostic biomarker in lung cancers." (PMID 32943616, 2020). "However, the biological function of DRAM1 in lung cancer remains controversial." (PMID 35884522, 2022). "On the other hand, the role of DRAM1 in lung cancer remains unclear." (PMID 35222643, 2022). "We confirmed that DRAM1 mainly localized to lysosomes (mCherry-LAMP1 positive), and later endosomes (GFP-RAB7 positive and GFP-RAB9 positive) in lung cancer cell." (PMID 32943616, 2020). "CCK-8 and transwell assays showed that overexpression of DRAM1 and inhibition of miR-524-5p significantly promoted lung cancer cell viability and invasion compared to the negative control groups." (PMID 35222643, 2022). "Knowing that DRAM1 is downregulated in lung cancer cells, we confirmed these observations in vitro and in vivo; we found that DRAM1 is upregulated in NSCLC tissues compared with adjacent nontumor tissues." (PMID 35222643, 2022). "Evidence revealed that DRAM1 could be a target of FTSJ1 and facilitate lung cancer progression." (PMID 35529878, 2022). "However, DRAM1 expression and clinical significance in lung cancer have not been elucidated." (PMID 35222643, 2022).
melanoma (5 papers, 2011 to 2026). A malignant, usually aggressive tumor composed of atypical, neoplastic melanocytes. "Only the module turquoise had a significant enrichment (p = 0.009) of genes whose homologs displayed prognostic value in melanoma, such as Oca2, Samhd1, Nlrc5, Irf1, Ifitm3, Sp100, Dram1, Rtn1, Tcaf2, Parp10, and Grin3a." (PMID 32831131, 2020). "In addition, we determined the expression of stress (CHOP, XBP1, and BIP) and autophagy (DRAM1, P62, ATG5, and ATG7) marker genes; furthermore, we successfully developed an HA15-resistant melanoma cell line." (PMID 33498201, 2021).
Cerebral ischemia (3 papers, 2014 to 2021). Restriction of arterial blood supply to the brain associated with insufficient oxygenation to support the metabolic requirements of the tissue. "During cerebral ischemia/reperfusion (I/R) injury, DRAM1 protein expression is increased, and autophagy is activated." (PMID 25342320, 2014).
cervical cancer (3 papers, 2022 to 2023). A primary or metastatic malignant neoplasm involving the cervix. "Similar results were observed in cervical cancer, in which Linc00511 could act as a ceRNA to regulate the miR-324-5p/DRAM1 axis, which had positive associations with tumor malignancy and poor prognosis." (PMID 35842617, 2022). "Another study showed that the lncRNA LINC00511 increases proliferation and invasion by sponging hsa-miR-324-5p to regulate DRAM1 expression in cervical cancer cells." (PMID 36685833, 2022).
colon cancer (3 papers, 2019 to 2024). "In addition, DRAM1 expression decreased in human colon cancer cells treated with anti-PD-1 nivolumab, suggesting that DRAM1 is a pro-cancer-associated autophagy gene, which is consistent with the results of this study." (PMID 37889013, 2023). "Using HEK293T cells as a positive control, we found that DRAM1 inhibited rpS6 phosphorylation in human colon cancer cells, SW480 and HCT116, with phosphorylation at Ser235/236 more significantly affected by DRAM1 than the site at Ser240/244." (PMID 30902093, 2019).
Mm (3 papers, 2020 to 2023). "Using a zebrafish model for Mm infection, we showed that knockdown or mutation of the zebrafish ortholog of DRAM1 causes a hyper-susceptibility to infection, while its overexpression increases host resistance against Mm." (PMID 36980169, 2023). "To study the localisation of DRAM1 in response to Mm infection in RAW264.7 macrophages, we performed immunofluorescence staining." (PMID 36980169, 2023). "This work extends our previous findings that Optn, p62 and Dram1 are important for resistance to Mm infection and confirms that their endogenous expression levels are not sufficient to provide full host resistance." (PMID 38264729, 2023). "We have recently shown that selective autophagy receptors are required to control Mm infection in zebrafish and that the host-protective function of Dram1 requires p62 in this infection model." (PMID 32332700, 2020). "The stimulatory action of DRAM1 on vesicle trafficking and fusion in the (auto)phagolysosomal pathway likely enhances the microbicidal activity against mycobacteria, as we observed that DRAM1 knockdown led to an overall increased Mm infection burden in RAW 264.7 macrophages." (PMID 36980169, 2023). "We found that Dram1 deficiency significantly increased Mm infection burden at 2 dpi but not yet at 1 dpi." (PMID 32332700, 2020). "Results showed that the percentage of infected cells in DRAM1 knockdown cell lines was higher than in the control group at 7 h post-infection, indicating that DRAM1 protects against Mm infection without affecting phagocytosis in RAW 264.7 macrophages." (PMID 36980169, 2023).
acute myeloid leukemia (2 papers, 2019 to 2020). Acute myeloid leukemia (AML) is a group of neoplasms arising from precursor cells committed to the myeloid cell-line differentiation. "While downregulation of DRAM1 gene suppressed autophagy and increased chemosensitivity of acute myeloid leukemia (AML) cells." (PMID 32393790, 2020).
acute myocardial infarction (2 papers, 2020). Necrosis of the myocardium, as a result of interruption of the blood supply to the area. "DRAM1 has been implicated in cancer, myocardial infarction, and infectious diseases, but the molecular and cellular functions of this transmembrane protein remain poorly understood." (PMID 32332700, 2020). "In acute myocardial infarction (AMI), DRAM1 exerted cardiomyocyte protection by increasing ATG7 expression and interacting with ATG7; additionally, DRAM1 enhances the conversion of autophagosomes to autophagolysosomes." (PMID 32943616, 2020).
autoimmune disease (2 papers, 2019 to 2021). A disorder resulting from loss of function or tissue destruction of an organ or multiple organs, arising from humoral or cellular immune responses of the individual to their own tissue constituents. "DRAM1 and NCL have been shown to be associated with other autoimmune diseases, such as Systemic Lupus Erythematosus and Multiple Sclerosis." (PMID 34177888, 2021).
hepatoblastoma (2 papers, 2020 to 2024). Hepatoblastoma (HB) is a malignant hepatic tumor and is the most common pediatric liver cancer. "Recent transcriptome analyses have unveiled that the genes GATA4, DPEP1 and DRAM1 exhibit high expression levels in hepatoblastoma tumor samples." (PMID 38390281, 2024). "Moreover, knockdown of the autophagy-related protein DNA damage-regulated autophagy modulator 1 (DRAM1) reduces the migrative and invasive capabilities of hepatoblastoma cells, inactivating autophagy, and EMT." (PMID 33194736, 2020).
lung adenocarcinoma (2 papers, 2019 to 2022). A carcinoma that arises from the lung and is characterized by the presence of malignant glandular epithelial cells. "Similarly, an mRNA expression database (containing 440 lung adenocarcinoma cases) for pro-autophagy markers was queried and the results showed that high expression of BECN1, ATG12, and DRAM1 are closely linked to increased survival among lung adenocarcinoma patients." (PMID 31101821, 2019).
preeclampsia (2 papers, 2022 to 2024). Preeclampsia is a hypertensive disorder of pregnancy that is characterized by new-onset hypertension with proteinuria presenting after 20 weeks of gestation, and depending on mild or severe forms may initially present with severe headache, visual disturbances, and hyperreflexia. "In this review, we compiled current studies investigating the role of BNIP3, DRAM1, and FUNDC1, mediators of receptor-mediated mitophagy, in the progression of preeclampsia and the role of mitophagy pathways in the pathophysiology of low birth weight." (PMID 36289801, 2022).
asthma (1 paper, 2024). "By using the LASSO algorithm, we identified five shared eosinophil‐associated hub genes (PPP1R14A, FNBP1, DRAM1, FSCN1, and MMP12) in asthma and CC." (PMID 39659035, 2024).
brain tumors (1 paper, 2019). "MCM5 is a proliferation marker in brain tumors, and expression of DRAM1 is related to neuronal autophagy." (PMID 31428131, 2019).
colitis (1 paper, 2022). Inflammation of the colon. "Thus, we explored the role of circGMCL1/miR-124-3p/DRAM1 network in colitis from the perspective of autophagy and NLRP3 inflammasome-induced pyroptosis." (PMID 36088391, 2022).